EPCAM (epithelial cell adhesion molecule)
Diseases named in the same sentence as EPCAM in open-access papers (continued):
Sharing a sentence is not in itself a finding about the gene and the disease.
cancer (continued). "Notably, the cell spheroids also expressed EpCAM, an epithelial cell adhesion molecule associated with epithelial tumor phenotype and cancer spreading." (PMID 30185225, 2018). "To study whether the method can detect an association of AGR2 and EpCAM, we required the use of cancer cell lines where AGR2 and EpCAM show mutual expression and where their assembly pathways are presumably intact." (PMID 29339412, 2018). "EpCAM has also been implicated as a marker for cancer stem cells (CSC)." (PMID 30572662, 2018). "Given the relative abundance of EpCAM in epithelial carcinomas, it may well serve as a useful diagnostic/prognostic biomarker and as a suitable therapeutic target." (PMID 30116994, 2018). "Although we did not detect PCDH18 mutations in the EpCAM-positive HCC cell lines, our data suggest that functional suppression of PCDH18, through somatic mutation or other mechanisms, may underlie the EpCAM-positive HCC cancer phenotype." (PMID 29075151, 2017). "In addition to these, other cancer stemness associated genes including EPCAM (1.6 folds), ALDH2 (1.3 folds), ALDH1A3 (0.9 folds) and HIF1A (0.7 folds) are all found up-regulated though to less extent." (PMID 28698547, 2017). "Furthermore, EpCAM is expressed on M2 polarized macrophages, for example, a subset of immune cells associated with a cancer phenotype." (PMID 27517159, 2016). "Consequently, the soluble variant of the extracellular domain of EpCAM (EpEX) has been found in sera of cancer patients." (PMID 25947366, 2015). "EpCAM-positive HCC cells also express markers associated with cancer stem cells and the epithelial to mesenchymal transition, supporting a hypothesis that EpCAM enrichment identifies stem-like cells with potential for metastasis." (PMID 25884197, 2015). "This paradoxical association of EpCAM expression with prognosis in different cancers may be explained by the functional studies of EpCAM biology using in vitro and in vivo cancer models." (PMID 25695234, 2015). "EpCAM overexpression strongly correlates with poor overall survival and bad prognosis and distinguishes patients at high risk for recurrence in a variety of cancers." (PMID 24727741, 2014). "EpCAM therefore has potential as a diagnostic and prognostic marker for a variety of carcinomas." (PMID 25019346, 2014). "However, there was a problem with this approach, because EPCAM protein expression was retained in some cancers from EPCAM mutation carriers." (PMID 23938213, 2013). "EpCAM is a widely described tumor-associated antigen, stem cell and cancer stem cell marker." (PMID 23758908, 2013). "However, we and others have found that the most dramatic phenotype associated with manipulation of EpCAM expression in human cancers is altered invasion." (PMID 22132731, 2011). "However, a reduction in surface expression of EpCAM has also been associated with aggressive cancers and poor prognosis in CRC." (PMID 21339979, 2010). "Epithelial cell adhesion molecule (EpCAM) is a 40 kDa transmembrane glycoprotein that serves important roles in cell adhesion, cell proliferation, differentiation, migration, cell cycle regulation and is implicated in cancer and stem cell signalling." (PMID 21152431, 2010). "Since flow cytometry is highly sensitive in detecting very low amounts of EpCAM-expressing cells, we believe that the results shown here represent a valuable proof in support of the hypothesis of a loss of viability of cancer cells, which occurs already after washing." (PMID 37373781, 2023).
cancer (continued). "Besides, EpCAM overexpression is related to Wnt/β-catenin pathway activation in cancers, which is a potential causal pathway for cytoplasmic and nuclear accumulation of β-catenin, indicating proliferation and reduced apoptosis in cancer cells." (PMID 35986321, 2022). "Hence, circulating EpCAM-positive exosomes could be a minimally invasive diagnostic marker for the early detection of cancers of epithelial origin or carcinomas." (PMID 32226524, 2020). "Although flow in our model is bidirectional due to the utilization of a pump-free rocker system, it would be of interest to test whether expression of genes previously implicated to affect migration in cancer, like EPCAM and integrin-β4 is affected in our interstitial flow model." (PMID 31546820, 2019). "This would suggest that the developed EpCAM aptamer could be used in therapeutic applications as a ligand for targeted delivery of cytotoxic drugs into tumors and cancer stem cells, as well as in diagnostic applications for identification of cancer cells." (PMID 29245156, 2017). "The epithelial-mesenchymal transition (EMT) has been associated with hematogenous cancer cell dissemination from the primary tumor to new organ sites, which may lead to a decrease in or loss of EpCAM expression and cannot be captured by a CellSearch-based isolation of CTCs." (PMID 27602758, 2016). "EpCAM is used as an epithelial marker to capture CTCs; however, it has been described as having dynamic expression (may be downregulated or absent) associated with EpCAM loss during dissemination into the blood, cancer progression and metastasis." (PMID 27711186, 2016). "However, increasing evidence has emerged that besides existence of significant amount of small size CTCs, clinical application of anti-EpCAM strategy is significantly limited due to inherent methodological deficiencies and intrinsic heterogeneity of cell biomarkers in cancer patients." (PMID 26267323, 2015). "Hence, because of driver mutations and over-production of TGF-β, cancer cells with EPCAM overexpression will easily unbind from the neighbour cells increasing their chance of reaching the local blood vessels and becoming CTCs; therefore, only cells with φ > 0 contributes in generating CTCs." (PMID 25978366, 2015). "Thus, while EpCAM is clearly useful in identifying CTC populations in many cancers, the biases associated with EpCAM enrichment are currently unknown." (PMID 22558290, 2012). "Furthermore, loss of EpCAM expression seen in de-differentiated states such as epithelial-mesenchymal transition and in cancer stem cells, in which EpCAM expression may be undetectable." (PMID 23171028, 2012). "In vitro studies demonstrated that CAR-M@Mn@ELE selectively targeted and killed 4T1 cancer cells (EpCAM+), while the hydrogel exhibited potent antibacterial activity against Escherichia coli (E. coli) and Staphylococcus aureus (S. aureus)." (PMID 42057107, 2026). "Cancer cell lines with heterogeneous frequencies of EpCAM‐positive cells and of various cell sizes were chosen to reflect the heterogeneity of CTCs and test the ability of the bioaffinity CTC filtration membrane to enrich cells with different characteristics." (PMID 41144783, 2026). "Clinical studies demonstrated that radiolabeled DARPins can be used for highly specific visualization of expression of other molecular targets, HER2 and EpCAM in malignant tumors." (PMID 41226646, 2025). "It is also noteworthy that expression of EpCAM was higher in cancer tissue compared to adjacent tissue." (PMID 40778224, 2025). "In conclusion, the armoring of the carcinoma-directed peptide–HLA-I fusion protein EpCAM-ReTARGTPR with IFNαR149A potently enhanced the efficacy of pre-existing anti-CMV CD8pos T-cell immunity to selectively eliminate EpCAMpos cancer cells." (PMID 40243928, 2025). "Transwell assay was also performed to examine effect of the five anti-EpCAM sdAbs on cancer cell invasion using the transwells coated with matrigel." (PMID 40017594, 2025).
cancer (continued). "EpCAM is a transmembrane glycoprotein with various cellular functions, contributing to cancer stem cell maintenance, proliferation, invasion, metastasis and therapeutic resistance." (PMID 39846613, 2025). "As a result, there has been much enthusiasm and fervor in researching EpCAM-directed CAR-T-cell therapies for various cancers, especially given the success in mice." (PMID 40869256, 2025). "EpCAM-targeted antibodies exhibit anticancer activity against tumors or CSCs not only by directly targeting cancer cells but also by regulating the expression of immune checkpoint inhibitors." (PMID 39996844, 2025). "As it can be inferred, THCs are identified by the expression of hematopoietic markers, including CD14, CD45 and CD163, provided by the myeloid partner, as well as common cancer-related markers (e.g. cytokeratin or EpCAM)." (PMID 39967663, 2025). "Both patients had decreased ascitic fluid production with reduced EpCAM-positive cancer cells in ascites samples." (PMID 40612946, 2025). "Ep-CAM-based CTC detection technologies are commonly used for malignancies such as breast and prostate cancer; however, EpCAM expression differs throughout cancer types." (PMID 40647654, 2025). "In particular, future work will include further phenotypical characterization for example through live imaging of specific markers like vimentin or EpCAM, indicating (changes in) mesenchymal and epithelial phenotype of cancer cells." (PMID 40585039, 2025). "A proportion of EPCAM+ cancer cells (median, 21,286; range, 129–197,205) expressed HLA-DRA, with a median ratio of 10.28% (range, 1.08–79.6%)." (PMID 40925909, 2025). "Taken together, this review explored the potential of EpCAM as a biomarker for early cancer detection, as well as a target for innovative therapies, including CAR-T cells, monoclonal antibodies, and EpCAM-labeled drug delivery systems." (PMID 39996844, 2025). "In this study, three EpCAM+ cancer cell lines, HCT116, A549, and MD-231, were selected as models for different expression levels of EpCAM to explore the feasibility, accuracy, and sensitivity of this exosome detection method." (PMID 39911266, 2025). "Specifically, cancer-associated genes, including VEGF-A, NR4A3, Ki-67, and EpCAM, were significantly down-regulated." (PMID 40359186, 2025). "This analysis revealed the strong expression of epithelial cell markers such as EpCAM and MUC-1 (approximately 70–60%), along with other cancer-associated markers, including TTF-1, Ki67, cytokeratin, and CD56." (PMID 39941799, 2025). "For example, classic molecular indicators of cancer, such as EpCAM and PD-L1, can be expressed on sEV surface to serve their immunosuppressive and tumor progressive functions." (PMID 41404198, 2025). "The expression of EpCAM is upregulated by 100- to 1000-fold in several primary carcinomas compared to normal tissues, underscoring its significance as a cancer stem cell marker." (PMID 40316530, 2025). "Cell scratch assay was performed to examine effect of the anti-EpCAM sdAbs on cancer cell migration." (PMID 40017594, 2025). "Subsets of CTCs expressing cell surface markers such as CD90, EpCAM, CD133, and vimentin have been associated with cancer stemness and epithelial–mesenchymal transition (EMT), and reports on these subsets are increasing." (PMID 40940925, 2025). "Within the framework of promoting personalized cancer therapy, this research highlights the potential of EpCAM–NIR–PIT as a multimodal platform." (PMID 40964888, 2025). "Together, these findings suggest that EpCAM-ReTARGTPRIFNαR149A has direct antiproliferative activity towards cancer cells and simultaneously promotes anticancer capacity, cytokine production, and the viability of TPR-specific CD8pos T cells." (PMID 40243928, 2025).
cancer (continued). "For the overall group analysis, patients in Groups 1 and 2 displayed similar expression patterns, particularly the downregulation of cancer-associated genes (Fas, NOS2, VEGF-A, NR4A3, MKi67, and EpCAM), as well as the pro-inflammatory cytokine IL-6." (PMID 40359186, 2025). "Polyethylene glycol (PEG) dendrimers with EpCAM aptamer were able to deliver celastrol, an anti-cancer agent, to induce apoptosis in SW260 colon cancer cells in vitro and in mice." (PMID 40650240, 2025). "Transwell assay was also performed to examine effect of the five anti-EpCAM sdAbs on cancer cell migration." (PMID 40017594, 2025). "Consistent with this, another study revealed frequent co-expression of TROP2 and EpCAM in cancers of the urinary bladder, prostate, pancreas, breasts, and ovaries." (PMID 40806559, 2025). "Catumaxomab was approved in Europe in 2009 for the treatment of malignant ascites, or fluid-containing cancer cells in the peritoneum of patients with EpCAM-positive carcinomas." (PMID 40869256, 2025). "The EpCAM intracellular domain is increased in cancer cells of breast, prostate, head and neck and esophagus compared to their corresponding normal tissues with EpCAM cell membrane localization." (PMID 40017594, 2025). "Their work allowed cancer cell isolation/enrichment, optical imaging, multiplex SERS detection for four cancer biomarkers (EpCAM, HER2, CD44, and IGF1R), as well as molecular profiling of various breast cancer cell lines." (PMID 39997827, 2025). "Epithelial cell adhesion molecule (EpCAM) is the most widely employed marker for CTCs in a variety of cancers as the source of most CTCs is epithelial cells." (PMID 40109625, 2025). "Taken together, our data demonstrate that both EpCAM-ReTARGTPRvIL2 and EpCAM-ReTARGTPRIFNαR149A selectively bind to EpCAMpos cancer cells, whereupon their respective cytokine muteins attain enhanced biological activity." (PMID 40243928, 2025). "We evaluated the cytotoxic effects of M701, mediated by CIKs, on cancer cells expressing different levels of EpCAM." (PMID 41275209, 2025). "There was a 3.3-fold increase in HPA binding of plasma-enriched EpCAM-positive sEVs from cancer patients compared to those from healthy individuals overall (p < 0.0001)." (PMID 40411659, 2025). "In various cases of ovarian cancerous peritonitis, EpCAM/LVRN double‐positive cancer cells were detected in ascites." (PMID 41024351, 2025). "The findings from this study are expected to provide valuable insights into the practical application of EpCAM-targeted NIR-PIT in cancer therapy." (PMID 40792441, 2025). "Several therapeutic approaches for targeting EpCAM in different cancers using antibody derivatives have been evaluated in preclinical models and in clinical trials." (PMID 40508045, 2025). "Of the 48 LNs that harbored cancer cells, 100% of them had fluorescence to some degree which was indicative of EpCAM expression." (PMID 41087662, 2025). "Epithelial cell adhesion molecule (EpCAM) is a transmembrane glycoprotein often highly expressed in various cancers." (PMID 40792441, 2025). "In this study, we aim to evaluate the effectiveness and feasibility of EpCAM-targeted NIR-PIT against cancers." (PMID 40792441, 2025). "The clinical relevance of EpCAM imaging is emphasized by its heterogeneous expression across various cancer types and within individual tumors." (PMID 40445498, 2025). "The results revealed that EPCAM was highly expressed in CNV cancer cells, while SFN was expressed at low levels." (PMID 40244296, 2025). "EpCAM is also considered one of the cancer stem cell markers, making it a promising target for NIR-PIT." (PMID 40792441, 2025). "Subsequently, MCC cells were treated with a dose range of 0.001–10 nM of EpCAM-ReTARGTPR, EpCAM-ReTARGTPRIFNαR149A, and rhIFNα, respectively, which reduced cancer cell viability by half." (PMID 40243928, 2025).
cancer (continued). "The cancer cells expressed L1CAM (CD171) and EPCAM (CD326), which are prognostic/diagnostic biomarkers often overexpressed on cancer cells, with roles in supporting cell motility, invasion, proliferation, and metastatic progression." (PMID 41279931, 2025). "Both EpCAM and Trop2 are strongly expressed in a large number of cancer cell lines and multiple types of human cancers." (PMID 39572744, 2025). "This study demonstrated that EpCAM-targeted NIR-PIT effectively eradicates EpCAM-positive cancer cells in both human and mouse models." (PMID 40792441, 2025). "The areas of EpCAM expression in the positive LNs was consistent with areas of cancer cells in the LN." (PMID 41087662, 2025). "Then, we used these monovalent format antibodies against EpCAM or CLDN3 to test their binding and internalization activity in OVCAR-3 and NCI-H1781 cancer cells, ultimately obtaining five EpCAM antibodies and three CLDN3 antibodies that met the requirements." (PMID 40057807, 2025). "Many TACT markers used in the present study, such as EPCAM and MKI67, have been implicated in fundamental biological processes relevant to various cancer types, including cell proliferation and EMT." (PMID 40003943, 2025). "Since EpCAM is known to promote cancer progression through β-catenin and NF-κB signaling, we focused on investigating its interaction with NAG-1/GDF15." (PMID 40316530, 2025). "In this phase IIA clinical study, upregulated expression of cancer-associated genes, including those linked to tumorigenesis and metastasis, such as VEGF-A, NR4A3, MKi67, and EpCAM were detected as early as Day 1 in the iCCA patients (Groups 1, 2, and 3)." (PMID 40359186, 2025). "In the case of HER2- and EpCAM- targeting DARPins, the internalization by cancer cells was slow, and the tumor retention was good." (PMID 41226646, 2025). "This study provides compelling evidence that targeting EpCAM with sdAbs is a promising approach for cancer treatment." (PMID 40017594, 2025). "Clinical trials have demonstrated that DARPin-based radionuclide imaging probes can successfully target and visualize cancer-associated upregulation of proteins in malignancies, for example DARPin G3 targeting HER2, and Ec1 targeting EpCAM." (PMID 40445498, 2025). "Epithelial cell adhesion molecule (EpCAM), a 30–40 kDa type I glycosylated membrane protein, is one of the target surface proteins commonly used in immunodiagnostic methods in cancer." (PMID 40951684, 2025). "In 120 h target/effector cell co-culture experiments, EpCAM-ReTARGTPRIFNαR149A significantly reduced the viable cell number of EpCAMpos cancer cells compared to EpCAM-ReTARGTPR." (PMID 40243928, 2025). "Since EpCAM is a common biomarker for cancer, an EpCAM monoclonal antibody was used to recognize TAE surface antigens." (PMID 39911266, 2025). "EpCAM-based therapies face several challenges, primarily due to the heterogeneity and plasticity of cancer cells." (PMID 39996844, 2025). "Taken together, the armoring of the carcinoma-directed peptide–HLA-I fusion protein EpCAM-ReTARGTPR with IFNαR149A potently enhanced the efficacy of pre-existing anti-CMV CD8pos T cell immunity to selectively eliminate EpCAMpos cancer cells." (PMID 40243928, 2025). "Our analysis identified E2F4 and TFDP1, two core components of the DREAM transcriptional repression complex, as transcriptional modulators preferentially activated by irinotecan in EPCAM+/CD44+/CD166+ as compared to EPCAM+/CD44neg/CD166neg cancer cells." (PMID 39896677, 2025). "Cancer-cell membrane (CCM) proteins such as EpCAM, E-cadherin, and integrin αvβ3 mediate adhesion to disseminated tumor cells (DTCs) in secondary organs, increasing nano-drug enrichment by 2–3-fold compared with PEGylated controls." (PMID 41155938, 2025).